PPARA (peroxisome proliferator activated receptor alpha)
Diseases named in the same sentence as PPARA in open-access papers (continued):
Sharing a sentence is not in itself a finding about the gene and the disease.
melanoma (69 papers, 2006 to 2026). A malignant, usually aggressive tumor composed of atypical, neoplastic melanocytes. "Later, PPARα deficiency was also proposed to impair regulatory T-cell functions, leading to the inhibition of melanoma growth." (PMID 35954274, 2022). "Stimulating the production of β-HB in melanoma and glioblastoma cells by a peroxisome proliferator-activated receptor-α (PPARα) agonist can cause tumor cell growth arrest." (PMID 36432116, 2022). "In addition, under the harsh condition of glucose and oxygen deficiency, CD8+ TILs isolated from melanoma samples combat tumor cells by upregulating PPARα signaling and enhancing FAO to fuel their energetic demands." (PMID 39872079, 2022). "To investigate the functional role of PPARα in the immune response, we challenged WT, A10-PPARα, and A10-PPARα-Cre mice with subcutaneous injections of murine melanoma B16-F10 cells." (PMID 39910334, 2025). "CD8+ TILs exhibited enhanced Peroxisome proliferator-activated receptor alpha (PPAR-α) signaling and fatty acid catabolism in both mouse models and melanoma patients, which is critical for their ability to suppress tumor growth." (PMID 40617808, 2025). "The researchers also found that PPARα was up-regulated and FAO was enhanced in BRAF-mutated melanoma cells after MAPK inhibition therapy, leading to cancer cell resistance." (PMID 40514365, 2025). "To further confirm the importance of this pathway in DNA damage‐induced cell death, we performed allograft assays with PPARα knockdown melanoma cells to assess changes in drug‐sensitivity." (PMID 38145969, 2024). "From studies of melanoma cells, 1,25D3 treatment increased the expression of PPARα and PPARδ, and treatment with PPARα and PPARδ ligands increased VDR expression." (PMID 39273194, 2024). "To assess the functional role of PPARα in the immune response, we challenged WT, A10-PPARα, and A10-PPARα-Cre mice with subcutaneous injection of murine melanoma B16-F10 cells." (PMID 38746124, 2024). "In melanoma, PPARα activation has been proposed to reduce metastatic potential via the down-regulation of AKT." (PMID 37237519, 2023). "It has been described that the PPARα activators fenofibrate and WY-14643 upregulated p38 phosphorylation in melanoma cells and in a mouse brain endothelial cell line." (PMID 37175404, 2023). "PGC1α-mediated mitochondrial oxidative phosphorylation (OXPHOS) and PPARα-mediated fatty acid oxidation (FAO) are 2 metabolic pathways that have emerged as promising targets to overcome therapy resistance in melanoma." (PMID 37616051, 2023). "Another study identified the peroxisomal enzyme ACOX1, a downstream target of PPARα, as a mediator of drug tolerance generally in melanoma persister cells." (PMID 37616051, 2023). "PPARα is poorly expressed in melanoma, and fenofibrate (an agonist of PPARα) can inhibit the metastasis of melanoma via the downregulation of AKT and ERK1/2 phosphorylation." (PMID 33959154, 2021). "PPAR pathway is suggested to be a potential target in melanoma, and PPARα and PPARγ receptors are overexpressed in melanoma cell lines compared to normal melanocytes." (PMID 31089369, 2019). "PPARα is a ligand-activated transcription factor that is involved in various skin diseases, such as psoriasis, acne, atopic dermatitis, scleroderma and melanoma." (PMID 28915638, 2017). "In clinical trials, fewer patients treated with gemfibrozil, a PPARα agonist, were diagnosed with melanoma compared with the control group." (PMID 28915638, 2017). "Here, we report a novel observation that fenofibrate, a synthetic peroxisome proliferator-activated receptor alpha (PPARa) agonist, induces bHB production in melanoma and glioblastoma cells, as well as in neurospheres composed of non-transformed cells." (PMID 26869992, 2016). "In this study, we show that cancer cells of neuroepithelial origin, namely melanoma and glioblastoma, can abundantly produce bHB when treated with fenofibrate, a potent PPARa pharmacological agonist and a hypolipidemic drug." (PMID 26869992, 2016).
melanoma (continued). "Here we present a comprehensive study assessing the anti-tumorigenic effects of a panel of PPARα and PPARγ agonists on a variety of melanoma cell lines." (PMID 23049949, 2012). "Several PPARγ agonists inhibit the proliferation of human malignant melanomas, and the PPARα agonist fenofibrate has antimetastatic effects on melanoma tumors in vivo in a hamster model." (PMID 19125181, 2008). "Recentstudies have revealed that PPARα is commonly expressed in tumour cell lines, including lung, liver,leukaemia, prostate, pancreas, bladder, colon, glioblastoma, hemangioma,melanoma, ovarian, and breast." (PMID 19043612, 2008). "B16-BL6 and B16-F10/GFP melanomas in PPARα KO mice contained high levels of TSP-1 protein, despite that these tumor cells do not express TSP-1." (PMID 17327920, 2007). "Notably, the protein levels of PPARα and PPARγ were higher in mouse and human melanoma cells than in normal melanocytes." (PMID 36834531, 2023). "For example, in BrafV600E melanoma preclinical models, the progressive loss of CD8+ T cell response is partially restored through the over-activation of PPARα-driven FAO in an oxygen- and glucose-deprived TME, using PPARα agonist, like fenofibrate." (PMID 35945203, 2022). "Over the years, researchers have discovered that PPARα may be a potential target in managing leukemia, melanoma, breast cancer, colon cancer, and glioblastomas." (PMID 33959154, 2021). "However, the same group demonstrated one year later that treatment with the PPARα agonist fenofibrate inhibited tumor growth in syngenic LLC1 or B16 melanoma tumor bearing mice, due to an increase of TSP-1 and inhibition of tumor angiogenesis." (PMID 32785018, 2020). "Importantly, PPARα inhibition also enhanced the anti-tumor efficacy of PD-1 antibody in the less immunogenic B16/F10 melanoma model." (PMID 33086073, 2020). "Using subcutaneous implantation of syngenic Lewis lung carcinoma (LLC1) or B16 melanoma cells in PPARα deficient mice, the authors demonstrated that tumor growth is prevented in the absence of PPARα." (PMID 32785018, 2020). "It was concluded that PPE may have a potential implication in melanoma treatment through activation of PPARα and PPARγ receptors." (PMID 31089369, 2019). "Contrary to what is stated, PPARα activity could be useful to counteract tumor progression in some tissue, as evidenced in melanoma." (PMID 29966227, 2018). "Recent studies indicate that PPARα, which iscommonly expressed in many tumor cell lines, could suppress colon carcinogenesis tumor development and inhibit melanoma cell metastasis." (PMID 28427159, 2017). "However, in this paper, we present a novel observation that malignant cells of neuroectodermal origin, namely melanoma and glioblastoma cells, are capable of efficient synthesis and release of bHB when treated with a synthetic PPARa agonist, fenofibrate." (PMID 26869992, 2016). "Additionally, PPARα agonist fenofibrate and PPARγ agonist pioglitazone have been shown to enhance the antitumor activity of cytotoxic T lymphocytes and invariant natural killer T cells in melanoma, respectively." (PMID 39735727, 2024). "This hypothesis is also applicable to CD8+ T cells, as synergistic antitumor effects of combined PD-1 blockade and PPARα agonism (i.e. by fenofibrate or bezafibrate) are observed in several cancer models, including colon carcinoma, melanoma, and lung carcinoma." (PMID 39872079, 2022). "Using syngenic implantation of B16 melanoma, LLC1 lung carcinoma, and SKOV-3 ovarian cancer xenograft models, the efficiency of the tumor growth-inhibiting properties of the PPARα antagonist NXT629 has been demonstrated." (PMID 35954274, 2022). "For example, the BRAFV600E melanoma cells increase their CD36 cell-surface levels and PPARα-dependent FAO to overcome the MAPK inhibitor effects." (PMID 35945203, 2022). "Ibuprofen, an activator of PPARα, was found to increase expression of CD36, the anti-angiogenic Thrombospondin-1 (TSP-1) receptor in human melanoma cells." (PMID 32785018, 2020).
melanoma (continued). "The cell lines used were aggressive B16 F10 murine melanoma and human glioblastoma LN229, which both show detectable levels of endogenous PPARa expression." (PMID 26869992, 2016). "These compounds are selective antagonists of the CB1, TRPV1, PPARα, PPARγ and GPR55 receptors respectively, the mRNA of which were found in B16 melanoma cells." (PMID 22429826, 2012). "Anti-migratory effect of fenofibrate towards melanoma cell lines has also been previously reported confirming the involvement of PPARα in cancer metastasis; however, the role of PPARα in melanoma metastasis is not fully elucidated." (PMID 36834531, 2023). "Since melanoma is a genetically highly heterogenous disease, we were interested if CNR1, PPARα and TRPV1 are frequently mutated and therefore not accessible for inhibitory therapy." (PMID 37237519, 2023). "Although some studies exist on PPARα in melanoma, PPARγ has, to our knowledge, never been investigated in relation to TILs and survival in any form of cancer." (PMID 36230483, 2022). "Since downregulation of PPARα significantly suppresses CPT1A expression and subsequently suppresses FAO in melanoma cells, the hypothesis that activation of PPARα by WY-14,643 might affect CPT1A was raised." (PMID 36384580, 2022). "Unsurprisingly, there was a line of evidence to support our findings that activating PPARA could reduce metastatic nonsmall cell lung cancer growth and the protective role of PPARD in melanoma metastasis." (PMID 34490113, 2021). "Although the tumor-promoting effects of PPARα in hepatocarcinomas are clear, less is known about the roleof PPARα in human tumors.Generally, activation of PPARα by exogenous agonistscauses inhibition of tumor cell growth in cell lines derived from CRC,melanoma, and glialbrain tumors." (PMID 18551185, 2008). "To this end, we employed a murine B16-F10 melanoma model with or without PPARα agonist treatment." (PMID 39910334, 2025). "FFA supplies energy, affects biosynthesis, and regulates the endocrine system.FFA can also activate the PPARα signaling pathway to upregulate the expression of catabolic enzymes in hepatocytes and accelerate the progress of FAO in the mitochondria to enhance cancer cell migration in melanoma cells." (PMID 39220365, 2024). "There are no studies concerning the direct effect of PPARα on the proliferation of melanoma cells; however, clinical studies confirmed the beneficiary effect of multi-modal therapy, including agonists of PPARα, on melanoma progression." (PMID 36834531, 2023). "Another PPARα antagonist, NXT629, inhibited the enlargement of chronic lymphocytic leukemia and ovarian cancer in a mouse model, and only NXT629 administration immediately after transplantation exhibited anti-tumor effects in a B16F10 melanoma subcutaneous transplantation model." (PMID 33466690, 2021). "This suggests that in the melanoma cells we studied, either PPARa does not play a role as an HMGCS2 transactivator or that the process might also be regulated downstream of transcription – perhaps through altered protein stability or turnover rate." (PMID 26869992, 2016). "The PPARγ specific agonists 15-deoxy-Δ12,14 prostaglandin J2 (15d-PGJ2), troglitazone, and rosiglitazone inhibited cell proliferation in four melanoma cell lines dose-dependently, whereas a specific agonist of peroxisome proliferator-activated receptor alpha (WY-14643) did not exert this effect." (PMID 23049949, 2012). "LN229 glioblastoma cells responded to fenofibrate similarly to the melanoma cells, with enhanced bHB production, regardless of the presence of the PPARa inhibitor MK886 or the level of PPARa expression." (PMID 26869992, 2016).
colitis (58 papers, 2006 to 2026). Inflammation of the colon. "When mice were treated with PPARα agonist Wy-14643, there was a decrease in susceptibility to colitis." (PMID 35003101, 2021). "PPARα -/- KO mice have increased susceptibility to colitis and commensal dysbiosis." (PMID 39451206, 2024). "5-ASA, through PPARα receptor, and glucocorticoids, through acylethenolamide producing/degrading enzymes, reduces colitis-associated inflammation suggesting PPARα agonists or FAAH/NAAA inhibitors as potential drugs for the treatment of inflammatory bowel diseases in human." (PMID 22662201, 2012). "The data indicate that PPARα has anti-inflammatory effects in a mouse model of chemically induced colitis; PPARα-deficient mice exhibit enhanced inflammation; exposure to PPARα ligands controls colonic inflammation through inhibition of proinflammatory cytokines." (PMID 22991505, 2012). "In addition, it was perceived that upregulated PEDF by using fenofibrate (FB), the PPARα agonist, increased the susceptibility of mice to colitis but could be mitigated by PEDF-neutralizing antibodies." (PMID 39027319, 2024). "Thus, PPARα has been proposed to participate in the intestinal epithelial barrier system; absence of PPARα expression resulted in an increase of tight junction permeability associated with apoptosis in an animal model of experimental colitis." (PMID 22662201, 2012). "CPT1A downregulation exerts protective effects on DSS-induced colitis by suppressing PPARα signaling while also modulating PINK1-mediated mitophagy and reducing cellular ROS generation, thereby alleviating tissue damage induced by oxidative stress." (PMID 41563994, 2026). "There have been controversial animal studies on experimental colitis in different animal models with the PPARα agonist fenofibrate, and there is an ongoing phase II study on its use in ulcerative colitis, although the results are yet to be reported." (PMID 39451206, 2024). "PPARα was downregulated in experimental DSS-induced colitis in mice, and PPARα levels in the colon were increased by atorvastatin treatment." (PMID 39451206, 2024). "The PPARα agonist fenofibrate, a lipid-lowering drug, improves colitis by reducing IL-17 and IFN-γ production by Th1 and Th17 cells in IL-10 -/- KO mice, a murine model of IBD." (PMID 39451206, 2024). "Atractylodin shows anti-inflammatory effects in colitis by activating PPARα, which was supported by in silico, in vitro, and in vivo data." (PMID 36614242, 2023). "PPARα knockout mice display exaggerated barrier dysfunction in response to induced colitis or stress." (PMID 38110453, 2023). "PPARα activation protected against induced colitis in a rodent model for inflammatory bowel disease, and it enhanced intestinal barrier function in rhesus macaques with chronic gut inflammation and dogs with experimentally-induced DM23,33,34." (PMID 38110453, 2023). "Balanced agonism of PPARα/γ was predicted to modulate macrophage processes, ameliorate colitis, ‘reset’ the gene expression network from disease to health." (PMID 35288651, 2022). "Taken together, these findings indicate that PPARα/γ dual agonist PAR5359 is superior in ameliorating C. rodentium-induced colitis than either PPARα or PPARγ agonist used alone." (PMID 35288651, 2022). "PPARα/γ’s role (or the role of their agonists) in protecting the gut barrier has been evaluated primarily in DSS-induced colitis." (PMID 35288651, 2022). "Taken together, these findings suggest that dual agonists of PPARα/γ are sufficient to either resist network shift and/or reverse the disease network in the setting of colitis." (PMID 35288651, 2022). "Noteworthy, while the role of PPARγ in colitis has been investigated through numerous studies over the past 3 decades, the role of PPARα has been contradictory, and their dual agonism in IBD has never been explored." (PMID 35288651, 2022).
colitis (continued). "These transcriptome-wide impacts suggest that PPARα/γ dual agonist PAR5359 is superior in restoring colon homeostasis in C. rodentium-induced colitis than either PPARα or PPARγ agonist used alone." (PMID 35288651, 2022). "Another study used a recombinant protein (rSj16) taken from bacteria and demonstrated its effects on inhibiting PPARα as well as protecting against DSS-induced colitis in mice." (PMID 35003101, 2021). "Palmitoylethanolamide is an endogenous lipid able to exert immunomodulatory activities and restore epithelial barrier integrity in human models of colitis, by binding the peroxisome proliferator–activated receptor-α (PPARα)." (PMID 33986673, 2021). "The results of this study demonstrate that DSS-induced colitis is associated with suppressed gene expressions related to SAT browning and BAT thermogenesis, and their master regulators, PPARα and PGC-1α in both SAT and BAT." (PMID 33674694, 2021). "More recently, it was shown that PPARα activation diminished the therapeutic effects of rSj16 in dextran sulfate sodium (DSS)-induced colitis mice, indicating that the PPARα signaling pathway plays a crucial role in DSS-induced colitis progression." (PMID 32028670, 2020). "PPARα mediated the anti-inflammatory effect of glucocorticoid (GC) in a chemical-induced colitis mouse model." (PMID 32028670, 2020). "TLR4 expression is reduced in enteric glial cells by the endocannabinoid-related lipid ligand palmitoylethanolamine, in a PPARα-dependent manner, to inhibit NF-κB activation, which is associated with a reduction in severity of DSS colitis." (PMID 29515999, 2018). "More recently, we found that the promoted PPARα-UGTs axis is a driving factor in disturbing BAs homeostasis in DSS induced colitis mice." (PMID 28969019, 2017). "PPARα dependent signaling pathways have been claimed to be involved both in the exacerbation and the attenuation of colitis, the latter via enteric glia." (PMID 28223944, 2017). "Many studies have demonstrated that PPARα mediates the anti-inflammatory effect in mice with DSS-induced colitis or acute ischemia/reperfusion." (PMID 23776651, 2013). "Increased PPARα expression or enhanced PPARα ligand production can attenuate inflammatory process observed in current animal models of experimental colitis." (PMID 22662201, 2012). "Recent studies in experimental colitis suggested that PPARα ligands also have anti-inflammatory properties, which was enhanced after glucocorticoid treatment, but was weakened in PPARα-null mice." (PMID 22662201, 2012). "Immunohistochemical expression in active colitis epithelium confirmed a PPARα decrease, but showed a sharp NAAA increase and a NAPE-PLD decrease, which were partially restored to control levels after treatment." (PMID 22662201, 2012). "The secondary aim was to investigate the involvement of PPARα regulation in Il10−/− mice before and after colitis onset using gene network analysis." (PMID 20671959, 2010). "In various animal models of IBD, the activation of PPARα or PPARγ has anti-inflammatory effects in the intestine, resulting in decreased production of inflammatory markers and slower progression of colitis." (PMID 19125181, 2008). "Conversely, in another animal study, DSS-induced colitis in mice was exacerbated by fenofibrate treatment in a PPARα-dependent manner, based on the modulation of sphingolipid metabolism, upregulation of fatty acid β-oxidation, and RIPK3-dependent necrosis in the colon." (PMID 39451206, 2024). "Thus, atractylodin can be a good strategy for colitis therapy through inducing PPARα-dependent pathways." (PMID 36614242, 2023). "Because almost all studies evaluating PPARα/γ-modulators have been performed on the DSS-induced colitis model, we asked whether the PPARα/γ dual agonist PAR5359 can ameliorate colitis in this model." (PMID 35288651, 2022).